CRP (C-reactive protein)
Diseases named in the same sentence as CRP in open-access papers (continued):
Sharing a sentence is not in itself a finding about the gene and the disease.
infection (continued). "Markers of inflammation and infection, such as C-reactive protein, interleukin-6, and procalcitonin, also demonstrated significant reductions." (PMID 38790912, 2024). "The most commonly used is CRP, which has been considered a marker of the systemic inflammatory response and a prognostic factor in infections and burns for quite some time already." (PMID 38792336, 2024). "Sensitive antibiotics were used in both intravenous and topical approaches after the operation, and the serum ESR, CRP, synovial fluid cell count, and CRP were used to monitor the control of infection." (PMID 39702276, 2024). "Our investigation suggests that despite potential interference from factors like CRS, biomarkers such as PCT, IL-6, and CRP hold promise for early infection detection, particularly in severe cases." (PMID 38956649, 2024). "In the emergency department, CRP is measured in patients presenting with a variety of symptoms to aid detection and evaluation of infection, tissue injury or inflammatory disorders, and to guide antibiotic treatment decisions and therapy adjustment." (PMID 38188655, 2024). "The infection-related indicators, C-reactive protein (CRP), white blood cell (WBC) count, procalcitonin level and platelet count, were normal." (PMID 38519924, 2024). "While ESR and CRP often remained elevated despite infection clearance, the synovial WBC count proved the most reliable marker for detecting persistent infection, showing 78% sensitivity and 96% specificity." (PMID 39493345, 2024). "Our study found that CRP levels were significantly higher in GT patients, suggesting that patients with GT have manifestations of infection, higher levels of inflammation, and poorer vascular endothelial function." (PMID 38725871, 2024). "The EFFORT Study, in fact, revealed that dietary supplementation is less effective in those with severe inflammation (CRP > 100 mg/dl) compared to individuals with CRP concentrations ≤100 mg/L, independently of infection and illness severity." (PMID 39683535, 2024). "Patients diagnosed with OM had significantly higher blood markers indicative of infection upon admission, including elevated c-reactive protein (CRP) levels (p < 0.001) and increased leukocyte counts (p < 0.028)." (PMID 39202718, 2024). "The inflammatory markers of infection severity, especially CRP levels at diagnosis, were an independent predictor of death in CDIE." (PMID 39330882, 2024). "ROC curve analysis was performed to evaluate the predictive ability of IL‐6, PCT, and CRP absolute concentrations against infection efficacy." (PMID 38967137, 2024). "There is a positive correlation between CRP levels and the severity of the infection, as well as the extent of the affected areas, according to Rasnake and Dooley." (PMID 38716470, 2024). "In face of infection/inflammation the pentameric form of CRP, mainly produced in the liver, dissociates irreversibly into monomeric form that acts locally and has a pro-inflammatory effect, i.e., by activation of the classical pathway of the complement system." (PMID 38272880, 2024). "A comparison of the standard infection parameters leucocytes, CRP and PCT (p < 0.05) revealed that only the latter exhibited a significant difference between the two groups." (PMID 39576568, 2024). "Serum CRP levels remained consistent at <2 μg/mL throughout the course of infection at similar levels to those observed in the sentinels." (PMID 39297649, 2024). "Elevated concentration of CRP is a feature of several other irAE as well as infection, surgery, and, sometimes, tumour progression." (PMID 38171113, 2024). "Higher C-reactive protein levels usually indicate more severe inflammation and infection, suggesting a more pronounced systemic inflammatory response." (PMID 39660004, 2024). "On Day 18 of the occurrence of infection symptoms, fever and elevated CRP levels were still present, which led to the decision to discontinue vancomycin and meropenem administration." (PMID 39338963, 2024).
infection (continued). "CRP is an inflammation marker in the blood and synovial fluid that has extensive use for infection and inflammation diagnosis; however, synovial CRP is more specific and preferred over its serological value for PJI diagnosis." (PMID 39493345, 2024). "The infection parameters ranged from low values in the normal range (leucocyte count 4.76 thousand/μl; CRP 3 mg/l) to highly elevated CRP values of up to 319 mg/l and leucocyte counts of up to 41.1 thousand/μl." (PMID 39085702, 2024). "Further studies on adhesion prophylaxis in DIE surgery should also report on changes in inflammatory markers to avoid misdiagnosis of post-operative infection, which can occur due to misinterpretation of CRP levels." (PMID 39458233, 2024). "Despite decreases in these markers, ESR remained elevated in 54% and CRP in 21% of cases where infection had been controlled." (PMID 39493345, 2024). "This study also suggests the use of WBC count and CRP level as biomarkers for monitoring active infection in this patient population, which is similar to previous studies." (PMID 37947190, 2024). "As CRP serves as an inflammatory marker, it aids in determining the extent of the infection and the efficacy of the treatment administered." (PMID 39206427, 2024). "For identifying the infection, some factors such as fever, CRP test results, CSF parameters (WBC numbers, glucose level, and CSF culture results) should be considered to prevent misdiagnosis." (PMID 39810804, 2024). "The analysis of blood test results revealed that CRP was raised in the majority of hMPV-positive patients whereas the rest of the infection markers were inconclusive." (PMID 39524165, 2024). "The ferritin concentration difference between groups with malaria infection and non-infection was fairly constant at every decile of CRP in areas of moderate endemicity." (PMID 39450524, 2024). "Physicians can monitor disease activity, gauge the degree of inflammation, and inform treatment plan development by measuring CRP, which is often employed as a biomarker of clinical inflammation and infection." (PMID 38896174, 2024). "Conditions that affect CRP levels include rheumatoid arthritis, several cardiovascular diseases and infection." (PMID 38188655, 2024). "Produced in response to various cytokines after infection, ischemia, trauma and other inflammatory conditions, CRP is an acute-phase protein." (PMID 39064051, 2024). "CRP levels were modeled using generalized additive mixed-effects models (GAMMs) and observed up to 150 h after initial infection diagnosis." (PMID 39467995, 2024). "CRP, a liver-produced protein that mainly indicates an infection, inflammation, or tissue injury, was elevated in almost all patients with a mean value of 140 mg/L while its normal blood level is < 10 mg/L." (PMID 38378528, 2024). "Within hours of tissue damage, the liver produces CRP, an acute-phase infectious and inflammatory process protein that can indicate an infection or an inflammatory state." (PMID 38910781, 2024). "Blood infection parameters were relatively high, with average CRP levels of 175.7 ± 12.5 mg/L and leucocytes 15.3 ± 6.9 cells/L." (PMID 36623943, 2024). "After this first step we also observed a significant decrease of key biological markers of infection (CRP level and white blood count) within the next 14 days." (PMID 38943052, 2024). "We developed and validated a prognostic model based on four laboratory biomarkers—WBC, CRP, PCT, and BUN—to predict the severity of Omicron variant infection complicated with MI." (PMID 38361939, 2024). "CRP is an acute-phase protein that plays an important role in infection, immunity, and inflammation." (PMID 38698338, 2024). "CRP levels demonstrate rapid and sensitive changes in acute trauma and infection, thus reflecting alterations in the body’s inflammatory response." (PMID 38632641, 2024). "CRP levels were also significantly higher in patients with active infection until 7 days after decannulation." (PMID 39797141, 2024).
infection (continued). "Presepsin is a relatively new biomarker of infection characterized by a short half-life and more rapid elevation in serum levels compared to procalcitonin or C-reactive protein (CRP)." (PMID 39767206, 2024). "Serial sampling analysis in patients demonstrated that MVP levels significantly decreased within the first four days of successful antibiotic treatment for infection, whereas CRP levels showed a less-sensitive decline." (PMID 39338437, 2024). "CRP can rise 1000-fold within a few hours after the onset of stimuli such as infection, tissue necrosis, trauma, cancer, or various inflammatory diseases." (PMID 38398254, 2024). "From day 5 to 21, this patient suffered anti-infection treatment using meropenem, and the infection indicators (CRP, WBC, NEU, IL-6, and PCT) were measured." (PMID 39203510, 2024). "The CRP levels are known to increase dramatically in response to injury, tissue damage, infection, and inflammation." (PMID 38306574, 2024). "Among markers of postoperative infection, CRP is considered the most sensitive because the value of CRP correlates with the intensity of the inflammatory conditions." (PMID 39539898, 2024). "Conversely, CRP is produced by the liver in response to interleukin-6 (IL-6), which is generated during infection and inflammation." (PMID 39669267, 2024). "In contrast, CRP, an infection and inflammation marker, becomes detectable after six hours and peaks at 36-48 hours." (PMID 39830581, 2024). "Our study found that over two thirds of patients with URTIs underwent CBC and CRP to determine the origin of infection." (PMID 38786268, 2024). "Among serum proteins and inflammatory markers, C-reactive protein (CRP) is the first APP to increase at the onset of any infection or inflammation, and is frequently used as a sensitive marker of inflammatory processes." (PMID 39457917, 2024). "The value of CRP in patients with early infection after THA was significantly increased on day six postoperative." (PMID 39120214, 2024). "BUN level seems to be a more sensitive indicator of infection than white blood cell count, C-reactive protein or procalcitonin, according to subgroup analysis." (PMID 39085852, 2024). "CRP, a protein synthesized by the liver, plays a pivotal role in the body’s defense mechanisms in response to inflammation or infection." (PMID 38397968, 2024). "CRP, an inflammatory marker produced by the liver, and elevated levels of Hcy typically indicate tissue damage from infection." (PMID 39238889, 2024). "C-reactive protein (CRP), an acute-phase protein secreted by the liver, is elicited in response to proinflammatory cytokines, often triggered by infection, inflammation, or tissue injury." (PMID 39600934, 2024). "Procalcitonin has a slightly superior sensitivity than CRP at the beginning of the infection, since it rises rapidly in 2–4 h and peaks at around 6–12 h." (PMID 39858292, 2024). "CRP, an acute-phase protein, is triggered by different cytokines in reaction to infection, ischemia, trauma, and other inflammatory circumstances." (PMID 38685951, 2024). "Expected CRP response centiles (10th, 50th, 90th) estimated separately for different infection sources showed little difference to the overall centiles." (PMID 38599549, 2024). "The CRP is produced by the liver and released into the blood in response to tissue injury, inflammation, and infection." (PMID 39596303, 2024). "C-reactive protein (CRP) is an acute-phase protein of hepatic origin that increases in the blood following inflammation and infection." (PMID 38915456, 2024). "CRP is an acute-phase reactant protein produced by the liver in response to inflammation or infection." (PMID 38891863, 2024). "Studies have shown a positive correlation between C-reactive protein levels with the degree of infection and injury, which is necessary for evaluating the activities of acute inflammation and surgical trauma, as well as the efficacy of medications." (PMID 38794748, 2024).
infection (continued). "Serum PCT, IL-6, and CRP were valuable in early infection prediction post-CAR-T therapy, particularly PCT with the highest area under the ROC curve (AUC) of 0.897." (PMID 38956649, 2024). "PCT, when compared to CRP, demonstrates greater specificity as a marker for severe infections and complications." (PMID 38696304, 2024). "Given the importance of postoperative infection monitoring, obstetricians often conduct frequent monitoring of serum infection markers, including CRP and other indicators." (PMID 38992621, 2024). "C-reactive protein (CRP) is an acute-phase protein mostly generated in the liver after infection, inflammation, and tissue injury." (PMID 38172843, 2024). "In an acute presentation, a differential diagnosis is relatively easy because of the symptoms of infection (fever and severe pain) and increased white blood count and CRP." (PMID 39001422, 2024). "C-reactive protein (CRP) is an established acute-phase marker for infection, inflammation and tissue injury, used to guide clinical decision-making in primary and secondary care." (PMID 38188655, 2024). "Infection-related biomarkers such as hs-CRP, PCT and IL-6 levels are commonly utilized laboratory indicators in diagnosing and treating infectious lung diseases." (PMID 38576608, 2024). "In turn, CRP mediates inflammation and responses to infection, such as the complement pathway, apoptosis, phagocytosis, nitric oxide release, and cytokine production." (PMID 39453923, 2024). "Since its discovery by Tillet in 1930, CRP had been widely used in clinical settings as an indicator of infection response." (PMID 39347502, 2024). "During acute inflammation, infection, or trauma phases, CRP levels considerably increase, while under normal conditions they remain very low (<1 mg/L), making them widely used as a serum biomarker for inflammation." (PMID 39000169, 2024). "During the extended period of SARS-CoV-2 infection, various studies have analyzed the prognostic prediction of several infection factors, including CRP, PCT, and CKs." (PMID 39654974, 2024). "C-reactive protein (CRP), a commonly marker for inflammation and clinical infections, interacts with the complement system and augments its effects." (PMID 38293363, 2024). "In the current study, the WBC level, ESR, and CRP, procalcitonin, and presepsin levels were all significantly higher in the group with severe infections requiring amputation." (PMID 38673584, 2024). "The CRP and fibrinogen were the most sensitive markers that highlighted the intensity of the systemic response to the infection." (PMID 39064086, 2024). "Significantly, we first reported and established a model that combines PCT and CRP with higher accuracy, offering a novel approach to early infection diagnosis." (PMID 38956649, 2024). "For example, CRP is an acute phase reactant secreted mainly by the liver and released in high concentrations in blood after tissue injury or infection." (PMID 38671019, 2024). "As the intensity of infection diminishes, CRP levels fall rapidly, whereas AGP remains elevated over a longer period." (PMID 39061651, 2024). "The point-of-care CRP test, in this regard, provides a viable solution as it is a rapid yet sensitive test that can be used to confirm physicians’ suspicion of an infection, thus reducing uncertainty while keeping the added time pressure to a minimum." (PMID 39195002, 2024). "CRP is synthesized by the liver in response to infection, inflammation, and tissue damage, acting as a specific inflammatory indicator." (PMID 39536046, 2024). "C-reactive protein (CRP) serves as a conventional marker of systemic inflammation; it is primarily produced by hepatocytes and cardiovascular tissue in response to infection, cell invasion, or tissue injury." (PMID 38786970, 2024).
infection (continued). "Traditional markers of infection, such as serum C-reactive protein (CRP), PCT, and white blood cells (WBCs), are a useful adjunct for diagnosing APN in children, but their performance in this setting is limited." (PMID 39334613, 2024). "CRP an inflammatory marker, exhibits a sharp increase in plasma levels during infection or tissue damage." (PMID 40046178, 2024). "A study in Brazil identified several laboratory parameters that correlated with a higher risk of infection, such as elevated concentration of fibrinogen, alanine aminotransferase (ALT), and C-reactive protein (CRP)." (PMID 38251253, 2024). "The routine blood examination has been listed as a laboratory test in the “Diagnosis and Treatment of Influenza (2019 edition),” while CRP is a classic differential diagnosis indicator of infection." (PMID 38306568, 2024). "During an infection, inflammation in the synovial membrane can increase its permeability, allowing high levels of serum CRP to enter the joint and raise the levels of CRP in the synovial fluid." (PMID 38847648, 2024). "CRP is an acute-phase protein secreted by the liver in response to inflammation, infection, and chronic diseases(s)." (PMID 39765954, 2024). "The body produces CRP in response to infection, inflammation, malignancy, and trauma, making it a widely recognized clinical marker for detecting infection." (PMID 39075344, 2024). "Elevated inflammatory parameters, particularly preoperative CRP levels, were indicative of postoperative wound healing disorders or infections." (PMID 39063921, 2024). "Laboratory investigations including ESR, CRP, and synovial fluid analysis are crucial to exclude infection." (PMID 39544553, 2024). "Markers of infection, such as white cell count or C reactive protein, are indeterminant markers of soft tissue health." (PMID 38053264, 2024). "Integrating CRP with other indicators, such as white blood cell counts, improves the precision of predicting infection complications." (PMID 39598263, 2024). "Following asevere infection, CRP levels rapidly rise, serving as aneffective marker for inflammation within the body.Conversely, PCT is primarily secreted by the thyroidgland and typically maintains minimal concentrationsunder normal physiological conditions." (PMID 39139150, 2024). "C-reactive protein (CRP) is an acute-phase protein produced in response to infection, tissue damage, and ischemia." (PMID 38337519, 2024). "This test uses an algorithm combining 3 proteins—TRAIL (a member of the tumor necrosis family), IP-10 (interferon-γ–induced protein-10), and CRP—to capture the host's immune response to infection and points to the source using multiple biological pathways." (PMID 39441193, 2024). "FebriDx® is a CE-marked, single-use point-of-care test with markers for bacterial [C-reactive protein (CRP)] and viral [myxovirus resistance protein A (MxA)] infection, using finger-prick blood samples." (PMID 38708643, 2024). "In this study, the levels of CSF HBP, PCT, and CRP in the intracranial infection group were greater than those in the non-infection group." (PMID 39611102, 2024). "C-reactive protein levels escalated markedly with the frequency of infections, from 3.1 ± 1.2 mg/L in the group with one infection to 8.7 ± 3.3 mg/L in the group with more than three infections (p < 0.001)." (PMID 38892528, 2024). "CRP levels were also elevated in the anti-IL-10 treated animals at day 2 post-infection, as compared to controls." (PMID 38950078, 2024). "Gerlach described that significantly elevated infection markers, such as leukocytes and CRP, are observed only in early infections." (PMID 39727803, 2024). "During these follow-up visits, clinical symptoms and signs of infection should be monitored, and tests for CRP and ESR levels should be conducted." (PMID 39410610, 2024).